OR2S2 (olfactory receptor family 2 subfamily S member 2)
Description:
Odorant receptor.
Synonyms: OR37A; OST715
Tractability: Antibody: its Gene Ontology location is reachable by antibodies, with high confidence; UniProt places it where antibodies can reach, with medium confidence; UniProt predicts a signal peptide or a membrane-spanning region.
Gene: Protein-coding gene on chromosome 9 (35,957,108 to 35,958,154, reverse strand). Ensembl gene ENSG00000278889.
Subcellular location: Cell membrane
Pathways (Reactome):
Sensory Perception: Expression and translocation of olfactory receptors; Olfactory Signaling Pathway
Gene Ontology:
Molecular function: olfactory receptor activity; G protein-coupled receptor activity
Biological process: detection of chemical stimulus involved in sensory perception of smell; sensory perception of smell; G protein-coupled receptor signaling pathway
Cellular component: membrane; plasma membrane
Genetic constraint (gnomAD): Loss-of-function variants: 0 observed, 1.65 expected, observed/expected ratio (o/e) 0, 90% interval 0 to 1.49. That is too few expected variants to judge how well the gene tolerates losing a copy. Missense variants: 365 observed, 407.98 expected, observed/expected ratio (o/e) 0.89, 90% interval 0.82 to 0.98. Synonymous variants: 153 observed, 167.44 expected, observed/expected ratio (o/e) 0.91, 90% interval 0.8 to 1.04.
Homologues: Orthologues: macaque OR2S2 (96% identical), pig OR2S2 (86% identical), dog OR13C11B (84% identical), dog OR13C11C (84% identical). Paralogues in human: OR13C8 (66% identical), OR13C3 (66% identical), OR13C4 (65% identical), OR13C5 (64% identical), OR13C2 (63% identical), OR13C9 (63% identical), OR13D1 (58% identical), OR2K2 (55% identical), OR13J1 (49% identical), OR2D3 (47% identical), OR2G3 (47% identical), OR10A4 (47% identical), and 80 more.
Diseases named in the same sentence as OR2S2 in open-access papers:
OR2S2 is named in the same sentence as 1 disease in open-access papers, as found by Europe PMC text mining. Sharing a sentence is not in itself a finding about the gene and the disease. The quoted sentences say what the papers report.
cancer (1 paper, 2021). A tumor composed of atypical neoplastic, often pleomorphic cells that invade other tissues. "Survival analysis based on promoter methylation did identify four associated genes OR2S2, SMILR, RNU6-653P, and AC010543, although very little is known about their biologic function, and nothing is published related to cancer." (PMID 34112938, 2021).